ABCA7 (ATP binding cassette subfamily A member 7)
Diseases named in the same sentence as ABCA7 in open-access papers (continued):
Sharing a sentence is not in itself a finding about the gene and the disease.
dementia (21 papers, 2012 to 2025). Loss of intellectual abilities interfering with an individual's social and occupational functions. "Two of the three most frequently identified genes in recent exome-wide association studies in unrelated individuals (TREM2 and SORL1) were significantly associated with proxy AD/dementia in this study and the third gene (ABCA7) was nominally significant." (PMID 36750708, 2023). "We also performed gene-set analyses using gene-sets composed of genes implicated by common variants and found that ABCA7 was the only gene driving the association between the gene-sets and proxy AD/dementia." (PMID 36750708, 2023). "A study showed that non-dementia subjects with ABCA7 mutation (an AD-related risk gene) are manifested as the decline of memory generalization." (PMID 35386301, 2022). "Previous studies have shown that the effect of the APOE gene on the risk of cognitive decline and dementia was modified by other genetic factors, including ABCA7, SORL1, PICALM, CR1, BIN1, and TREM2, showing complex gene-gene interactions." (PMID 34214049, 2021). "There is prior evidence of increased expression of ABCA7, BIN1, and MS4A6A in LOAD brains, and increased ABCA7 expression is associated with clinical dementia rating, with higher expression being associated with more advanced cognitive decline." (PMID 26101835, 2015). "Although the relationships between AD and ABCA7 SNPs are well-characterized, there are limited studies on the association between genetic variation in ABCA7 and measures of cognitive function and/or cognitive decline prior to the development of dementia." (PMID 36421824, 2022). "Moreover, an enrichment in loss of function ABCA7 variants was observed in early onset AD patients, supporting its specific involvement in early onset dementia." (PMID 31405128, 2019). "The ATP‐binding cassette subfamily A member 7 (ABCA7) gene, linked to dementia in African Americans, and unique genetic variants like those in A‐kinase anchor protein 9 (AKAP9) and cytidine deaminase (CDA) genes, emerge as potential contributors." (PMID 40289851, 2025). "Our analysis validates the interdependence of AD, dementia, and Parkinson’s disease through various common genes (i.e., A2M, ABCA7, PLAU, PSEN2, and MPO)." (PMID 38790243, 2024). "Thus, in African Americans the interactive effects of ABCA7 rs3764650 and aerobic fitness likely compound overall ABCA7-related AD risk, and may contribute to health disparities whereby African Americans are at a higher risk for dementia, with double the prevalence of AD." (PMID 31024289, 2019). "Further research into ABCA7 inverse comorbidities is warranted to understand the implications of ABCA7 expression as a possible therapeutic target for dementia." (PMID 30903345, 2019). "We found that ABCA7, CD33, and CR1 expression levels were associated with clinical dementia rating (CDR), with higher expression being associated with more advanced cognitive decline." (PMID 23226438, 2012). "In the present study, we evaluated the association between ABCA7 genetic, epigenetic, and transcriptomic markers and cognitive function in 634 AA participants without preliminary evidence of dementia." (PMID 36421824, 2022). "Moreover, thanks to NGS approach, we disclosed other variants in dementia-related genes, in particular FUS, ABCA7, CSF1R, DCTN1, SERPINI1 and SORL1." (PMID 33006056, 2021). "As such, ABCA7 rs115550680 may confer AD risk selectively in African Americans, and, in conjunction with the indirect effects of ABCA7 rs3764650, may contribute to the higher incidence rate of dementia and AD in this population." (PMID 31749691, 2019). "In this study, we investigate whether previously identified risk SNPs (referred to as sentinel SNPs) in ABCA7, DNA methylation in ABCA7, and their interactions are associated with general cognitive function in older AA without dementia." (PMID 36421824, 2022).
dementia (continued). "Overall, variable disease penetrance and onset ages are observed, and it is currently not known whether ABCA7 variants are AD specific or if they contribute to other dementia phenotypes as well." (PMID 30903345, 2019). "Subjects with VaD/mixed dementia had 98% higher PICALM mRNA levels, but 75% lower ABCA7 mRNA expression than healthy individuals." (PMID 36982820, 2023). "More specifically, a CpG island shore, located in exon 12 and intron 12 of ABCA7 (chr19:1045074–1045679), was hypomethylated in LOAD when compared to healthy control brains, and brains of patients with dementia with Lewy bodies." (PMID 30903345, 2019). "Despite ABCA7 rs3764650 not being directly implicated in AD in African Americans, we hypothesized that it may yield an indirect risk through its interaction with other risk factors, which in turn, could account for the higher incidence rate of dementia and AD in this population." (PMID 31024289, 2019).
cognitive decline (15 papers, 2012 to 2025). "Among these, ABCA7 has been linked to cholesterol metabolism and cognitive decline, playing a significant role in neuronal health." (PMID 40565005, 2025). "By contrast, increased levels of ABCA7 have been described to occur in AD brains and positively correlate with disease severity, i.e., higher expression was associated with more advanced cognitive decline." (PMID 38247503, 2024). "This ABCA7 variant is associated with a later age of onset and shorter disease process, exacerbating cognitive decline in subjects diagnosed with mild cognitive impairment or AD." (PMID 31024289, 2019). "ABCA7 has previously been shown to be associated with AD, with increased levels of ABCA7 correlating to increased plaque burden and more rapid cognitive decline." (PMID 28549481, 2017). "An imaging study showed that ABCA7 SNPs were associated with amyloidosis among cognitively healthy individuals and those with mild cognitive impairment, but not among those with AD, suggesting an early effect of ABCA7 on cognition and cognitive decline." (PMID 36421824, 2022). "In LOAD, it is not clear whether ABCA7 expression is altered early in the disease; surprisingly, in advanced AD, ABCA7’s higher expression was associated with advanced cognitive decline." (PMID 32362813, 2020). "Our findings imply that ABCA7 rs3764650 risk genotype may diminish the neuroprotective effects of aerobic fitness, and, they suggest differing risk patterns between cognitive decline and fitness by ABCA7 genotype." (PMID 31024289, 2019). "The previous studies also found that ABCA7 SNPs were associated with brain amyloidosis, changes in gray matter density, and Braak staging, a measure of neurofibrillary tangle development, which is associated with cognitive decline (Lyssenko and Praticò, 2021)." (PMID 39484364, 2024). "Genotyping of selected single-nucleotide polymorphisms in the APOE, ABCA7, SORL1, BIN1, GAB2, and CD33 genes was conducted, and a Bayesian hierarchical model was fitted to analyze the trajectories of cognitive decline among different genotypes." (PMID 34214049, 2021). "The further cognitive decline that occurs in the cognitive functions of AD patients is explained by some researchers, by the high levels of ABCA7 and by the regulatory function of ABCA7 in phagocyte function." (PMID 34877572, 2021). "In this study, we found that ABCA7 expression levels are significantly associated with CDR, with higher expression levels of this gene being correlated with more extensive cognitive decline." (PMID 23226438, 2012). "Studies suggest that interactions between APOE ε4 and other genes, such as ABCA7, may accelerate cognitive decline and neurodegeneration." (PMID 40565005, 2025). "Subsequently, we attempted to address reasons for cognitive decline in older ABCA7 KO mice." (PMID 36007616, 2022). "On the other hand, large-scale studies found no, or complex associations between ABCA7 sentinel SNPs and cognitive decline." (PMID 30903345, 2019).
amyloidosis (12 papers, 2016 to 2025). A disorder characterized by the localized or diffuse accumulation of amyloid protein in various anatomic sites. "In Aβ pathology, altered amyloid precursor protein (APP) metabolism with the overproduction of Aβ peptides is the primary cause of amyloidosis, and APOEε4 and ABCA7 were identified to be most strongly associated with Aβ production." (PMID 38094504, 2023). "Moreover, several studies have found associations between common ABCA7 GWAS SNPs and decreased Aβ1–42 CSF levels or increased amyloidosis using imaging biomarkers." (PMID 37946268, 2023). "A strong association was demonstrated between ABCA7 variations and amyloidosis in AD patients." (PMID 33006056, 2021). "In APP/PS1 mice, ABCA7 deficiency increases Aβ levels and exacerbates the amyloid plaque burden." (PMID 32257549, 2020). "SAA receptors, such as SELS (glucose homeostasis and ER stress), ABCA1, ABCA7, SCARB1 (cholesterol efflux), CD36, TLR2, TLR4, CST3 (inflammatory signaling), FPR2 (chemotaxis and immune cell activation), and AGER (amyloidosis), have been reported previously." (PMID 27799725, 2016). "Crossing ABCA7 knockout mice to mutant hAPP mice caused a doubling of insoluble Aβ levels and amyloid plaques without changing APP processing, suggesting that like ApoE, ABCA7 is involved in Aβ clearance." (PMID 27025652, 2016).
Cognitive impairment (8 papers, 2012 to 2025). Abnormal cognition is characterized by deficits in thinking, reasoning, or remembering. "Research has found that the ABCA7 SNP (rs3764650) is significantly associated with cognitive impairment exclusively in women, while ABCA7 rs3764650 is only related to cognitive dysfunction in men." (PMID 38241287, 2024). "We observed that KO mice have diminished levels of SM in the brain, cognitive deficits, and that ABCA7 deficiency affects synaptic plasticity, whereas this effect is rescued by SM supplementation." (PMID 36007616, 2022). "We have recently shown that ABCA7 affects synthesis and export of SM and its deficiency in mice affects brain SM metabolism causing cognitive defects." (PMID 36297086, 2022). "The cognitive impairments of Abca7 deficient mice are in line with the expression profile of ABCA7, which is abundant in hippocampal and cortical neurons, suggesting a potential moderate role of the ABC transporter in cognitive domains." (PMID 23029339, 2012). "Accumulating evidence through genetic studies suggests that the contribution of ABCA7 to AD risk is mediated by the dysfunction of ABCA7 expression, such that, increased ABCA7 expression levels have been associated with more severe cognitive deficits in AD subjects." (PMID 31024289, 2019).
hippocampal atrophy (4 papers, 2019 to 2024). "The previous studies found that the ABCA7 gene rs3764650-G allele was associated with cortical and hippocampal atrophy, cognitive performance, and neuritic plaque burden." (PMID 39484364, 2024). "Clinically, the ABCA7 rs3764650 minor allele was associated with cortical and hippocampal atrophy and with a later age at onset and shorter disease duration." (PMID 34214049, 2021). "Regarding the effect of APOE-ABCA7 interactions on functional connectivity in the vDMN, previous studies have reported that the hippocampal atrophy is associated with ABCA7 rs3764650G allele and APOE-ε4 carriage." (PMID 31831047, 2019). "Furthermore, Abca7 which was related to multiple neurological diseases, in particular cortical and hippocampal atrophy." (PMID 39529156, 2024).
ovarian carcinoma (4 papers, 2018 to 2023). A malignant neoplasm originating from the surface ovarian epithelium. "In a study on epithelial ovarian cancer, intraperitoneal metastases showed significantly higher ABCA7 mRNA levels than primary tumors and control ovarian tissues." (PMID 37296582, 2023). "Silencing of ABCA7 reduces epithelial to mesenchymal transition in ovarian cancer cell lines and knockdown of ABCA7 inhibited migration, cell proliferation, and invasion." (PMID 33334016, 2020). "ABCA7 expression is increased in ovarian cancer tissues, and this upregulation has been shown to accelerate the epithelial-to-mesenchymal transition, a process involved in the initiation of metastasis." (PMID 30903345, 2019). "In vitro knockdown of ABCA7 in ovarian cancer cells reversed markers of epithelial-to-mesenchymal transition, suggesting that ABCA7 is actively involved in this process." (PMID 30903345, 2019). "In addition to ovarian cancer, increased expression of ABCA7 was observed in pancreatic ductal adenocarcinoma tumors." (PMID 30903345, 2019). "Furthermore, ovarian cancer patients with high ABCA7 mRNA expression levels, have a poorer survival rate than patients with low ABCA7 expression." (PMID 30903345, 2019). "In addition, CELF1 has been associated with certain types of cancer, and expression of ABCA7 significantly increased in ovarian carcinoma." (PMID 29723294, 2018). "In the same study, down-regulation of ABCA7 in the ovarian cancer cell line SKOV-3 decreased cell migration, increased E-cadherin levels, and decreased N-cadherin levels, suggesting a role of ABCA7 in epithelial–mesenchymal transition (EMT)." (PMID 37296582, 2023).
colorectal cancer (3 papers, 2018 to 2023). A primary or metastatic malignant neoplasm that affects the colon or rectum. "In addition, lower ABCA7 levels associated with shorter DFS of colorectal cancer patients." (PMID 33334016, 2020). "In a study on colorectal cancer, patients with low ABCA7 mRNA levels had shorter disease-free interval after adjuvant chemotherapy than those with high ABCA7 mRNA levels." (PMID 37296582, 2023).
Anxiety (2 papers, 2012 to 2022). Intense feelings of nervousness, tension, or panic often arise in response to interpersonal stresses. "Abca7 null mice have normal sensory abilities, neurological reflexes and motor functions and show wild type-like anxiety behaviour and sensorimotor gating." (PMID 23029339, 2012).
breast carcinoma (2 papers, 2023 to 2024). "In the present study, we investigated if specific epigenetic and genetic alterations and transcript variants of ABCA7 occur in breast cancer, and if detected alterations are associated with ABCA7 expression." (PMID 37296582, 2023). "We searched for specific epigenetic and genetic alterations and alternative splicing variants of ABCA7 in breast cancer and investigated whether these alterations are associated with ABCA7 expression." (PMID 37296582, 2023). "The ABC transporter ABCA7 has been found to be aberrantly expressed in a variety of cancer types, including breast cancer." (PMID 37296582, 2023). "Since breast cancer cells surviving Dox or Tax treatment showed pronounced alterations in retention/alternative termination of ABCA7 introns 3, 5, and/or 6, we used RBPmap to predict binding sites for RNA-binding proteins." (PMID 37296582, 2023). "Since the DNA methylation status of MDA-MB-453 at the ABCA7 exon 5–intron 5 boundary more closely resembled that of triple-negative than that of Her2-positive breast cancer cell lines, we suggest classifying MDA-MB-453 as triple-negative." (PMID 37296582, 2023). "We performed DNA methylation, SNP, mRNA expression, and alternative splicing analysis for ABCA7 as well as shotgun proteomics in order to identify breast cancer-specific alterations in breast tissues, cell lines, and cell lines upon treatment with Dox or Tax." (PMID 37296582, 2023). "The whole ABCA7 transcriptome and its regulation in breast cancer remains to be investigated in further studies, e.g., by RNA sequencing." (PMID 37296582, 2023). "Treatment of four breast cancer cell lines with Dox or Tax for 72 h resulted in altered retention of ABCA7 introns in a molecular subtype-specific manner." (PMID 37296582, 2023). "In order to elucidate if ABCA7 methylation status at the exon 5–intron 5 boundary is a marker for epigenetic field cancerization, we also determined the methylation status for tumor-adjacent and tumor-distant tissues from these breast cancer patients." (PMID 37296582, 2023). "The ABC transporter ABCA7, involved in lipid transport processes and cholesterol homeostasis, has been found to be aberrantly expressed in a variety of cancer types, including breast cancer." (PMID 37296582, 2023). "In addition, growing evidence suggests that adipocytes, reported to express ABCA7, have a promoting effect on breast cancer cells, presumably by secretion of a variety of molecules including inflammatory cytokines, hormones, adipokines, and lipid metabolites." (PMID 37296582, 2023). "However, we detected breast cancer-specific aberrant DNA methylation at the exon 5–intron 5 boundary of ABCA7." (PMID 37296582, 2023). "Thus, neither our results nor data from TCGA hint at an association of ABCA7 intron 1 methylation with breast cancer." (PMID 37296582, 2023). "Treatment of breast cancer cell lines MCF-7, BT-474, SK-BR3, and MDA-MB-231 with doxorubicin or paclitaxel for 72 h resulted in altered ABCA7 intron levels." (PMID 37296582, 2023). "Since RNA was not available from breast tissue samples, sample set 2, comprising 16 commercial breast cancer and two non-cancerous breast cell lines, was analyzed to detect any potential association between DNA methylation, SNP genotypes, gene expression, and alternative splicing of ABCA7." (PMID 37296582, 2023). "In patients with luminal A breast cancer, the CpGs at the ABCA7 exon 5–intron 5 boundary were not only more highly methylated in tumors but also in tumor-adjacent and tumor-distant tissues compared to normal breast tissues from cancer-free controls." (PMID 37296582, 2023). "In commercial breast cancer cell lines, DNA methylation of promoter–exon 1, intron 1, and the exon 5–intron 5 boundary was not correlated with ABCA7 gene expression." (PMID 37296582, 2023).
breast carcinoma (continued). "In breast cancer cell lines, DNA methylation levels of CpGs in promoter-exon 1, intron 1, and at the exon 5–intron 5 boundary were not correlated with ABCA7 mRNA levels." (PMID 37296582, 2023). "CpGs in the promoter–exon 1 region of ABCA7 showed rather low methylation levels in breast tumor tissues, which is in accordance with TCGA data, and breast tissues from cancer-free women, indicating that the DNA methylation status of CpGs in the promoter–exon 1 region is not breast cancer-specific." (PMID 37296582, 2023). "Since RNA was not available from breast tissue samples, we included sample set 2, consisting of 12 breast cancer cell lines and one non-cancerous cell line, to investigate whether DNA methylation of promoter–exon 1, intron 1 and exon 5–intron 5 boundary was correlated with ABCA7 expression." (PMID 37296582, 2023).
diabetes (2 papers, 2022 to 2025). "Caribbean and African individuals share a high rate of cardiovascular disease (including hypertension and diabetes) with South Asian groups: however, additional socioeconomic, environmental, and genetic factors (such as ABCA7 gene) also contribute to risk." (PMID 41234424, 2025).
melanoma (2 papers, 2014 to 2018). A malignant, usually aggressive tumor composed of atypical, neoplastic melanocytes.
Obesity (2 papers, 2020 to 2021). Accumulation of substantial excess body fat. "In line with this hypothesis, genes PTK2B, KANSL1 and ADAM10 have been previously associated with obesity and BMI, while ABCA7 and ADAM10 have been associated with blood pressure." (PMID 34992629, 2021). "Since the ABCA1, ABCA7 and ABCG1 proteins actmainly in the cholesterol metabolism, and cholesterol dysfunction in the adiposetissue could be related to a lipid imbalance in the whole body, geneticpolymorphisms in the corresponding genes could be involved in obesity-associatedmetabolic complications." (PMID 32745159, 2020).